RNU1-61P (RNA, U1 small nuclear 61, pseudogene)
Gene: Small nuclear RNA gene on chromosome 6 (32,549,940 to 32,550,090, reverse strand). Ensembl gene ENSG00000251916.
Homologues: Orthologues: macaque U1 (93% identical), chimpanzee U1 (84% identical), guinea pig U1 (56% identical), dog U1 (53% identical), mouse Gm55957 (51% identical), pig U1 (46% identical). Paralogues in human: RNVU1-7 (64% identical), RNU1-1 (63% identical), RNU1-138P (63% identical), RNU1-2 (63% identical), RNU1-27P (63% identical), RNU1-28P (63% identical), RNU1-3 (63% identical), RNU1-4 (63% identical), RNVU1-18 (63% identical), RNVU1-29 (63% identical), U1 (63% identical), RNU1-11P (62% identical), and 134 more.